KRAS (KRas proto-oncogene, GTPase)
Diseases named in the same sentence as KRAS in open-access papers (continued):
Sharing a sentence is not in itself a finding about the gene and the disease.
tumor (continued). "Previous studies have shown that the mutation rate of KRAS in patients with CRC is 37%–56%, and the mutation status is related to tumor size, tumor location, degree of tumor differentiation, lymph node metastasis, and other factors." (PMID 35837115, 2022). "Activating mutations were identified in tumor samples including EGFR L858R, EGFR T790M, EGFR exon 19 deletion, ERBB2 amplification, ALK fusion, KRAS G12C." (PMID 35123506, 2022). "In our study, 86% (25/29) of the DNAs from resected tissues, in which tumour remnants were expected (i.e. tumours of the UFS group and tumours of the ypT1 NAT sub-group), showed detectable KRAS mutations." (PMID 35194118, 2022). "Insufficient infiltration, dysfunction of TILs, and tumor evasion from T cell surveillance within the KRAS-driven tumor niche are well-known challenges in classical cancer therapy regimens." (PMID 35014625, 2022). "Collectively, the series of experiments revealed that the combination of CTX and PD effectively decreased tumor growth by decreasing cell proliferation (Ki67) and increasing cell death (apoptosis) in KRAS-mutant CRC cell lines." (PMID 36387129, 2022). "Contradictory evidence exists to show inhibition of KRAS leading to tumor regression, and KRAS-mutant cell lines exist whose growth and tumorigenicity do not depend on oncogenic KRAS, on the other hand." (PMID 36430528, 2022). "In comparison, the A549 NSCLC KRAS mutant xenograft model was less sensitive to the same dose of AZD0364 reaching only partial tumour growth inhibition (TGI)." (PMID 35617197, 2022). "In CRC, CD16-CAR T-cells combined with cetuximab decreased the viability of KRAS-mutated HCT116 CRC cells in vitro, decreased tumor growth in a SCID mouse model, and increased disease-free survival." (PMID 36458008, 2022). "SHP099 was found to significantly reduce tumor growth in patient-derived orthotopic xenografts and KRAS mutant NSCLC patient-derived xenograft models." (PMID 35251972, 2022). "Changes in tumor volume are presented for animals bearing isogenic SW48 cells: parental/KRAS WT, KRASG12D/+, KRASG12V/+, KRASG13D/+." (PMID 35879364, 2022). "This is a review presented oncogenic KRAS plays a critical role in controlling tumor metabolism by increasing autophagy and orchestrating other multiple metabolic changes." (PMID 36263211, 2022). "It is important that the combination of PTEN and KRAS genetic alterations led to appearance of aggressive tumor cells and the development of lung metastasis." (PMID 36613756, 2022). "KRAS/STK11 co-mutations represent 25% of KRAS-mutant NSCLC, characterized by the low presence of tumor-infiltrating lymphocytes and reduced immune markers and PD-L1 levels." (PMID 36012655, 2022). "Mechanistically, epithelial TGFβ signalling induces a growth-promoting EGFR-signalling module that synergises with mutant APC and KRAS to drive MAPK signalling that re-sensitise tumour cells to MEK and/or EGFR inhibitors." (PMID 36477656, 2022). "High DDR1 immunostaining score was significantly associated, on univariate analysis, with male sex, left tumor location, BRAF wild type status, KRAS mutated status, and Annexin A10 negativity." (PMID 35205677, 2022). "In total we found 15 of these transversions in KRAS positive tumor DNA (30.0%), which stands for 7.8% of all tumor DNA in our set." (PMID 35628513, 2022). "Reported risk factors for peritoneal seeding include tumor cell spillage during surgery of the primary CRC, locally advanced tumor stage (T4), lymph node metastases, right sided, mucinous or signet cell cancers, or aberrations in KRAS/BRAF signaling." (PMID 35927254, 2022). "Tumor samples from patients with ALK-rearranged (N = 39) and EGFR- (N = 40)/KRAS- (N = 30) mutated NSCLC were collected." (PMID 36159860, 2022). "Mechanistically, the KRAS status determines the transcriptional consequences of EZH2-dependent targeting of the NFATc1 gene, encoding for an inflammatory tumor-progressive transcription factor." (PMID 35884510, 2022).
tumor (continued). "Further residual tumor profiling using IHC showed marked reduction in the proliferation marker, Ki67 and inhibition of KRAS in the combination group." (PMID 35573474, 2022). "It was observed that the inhibition of KRAS and ERK1/2 together in tumor cells synergistically increased the cytotoxicity causing cell death." (PMID 36230831, 2022). "Monoclonal antibodies against the vascular endothelial growth factor (VEGF) or, in patients with KRAS/NRAS wild-type tumours, against the epidermal growth factor receptor (EGFR) are commonly added to chemotherapy in mCRC." (PMID 35574322, 2022). "In vivo analysis was also performed to observe the cetuximab-resistant KRAS-harboring CRC tumor in the Xenograft mouse model." (PMID 35409064, 2022). "Among the 34 enrolled patients, one patient exhibited focal EGFR and KRAS amplification, which occurred concurrently in progressive tumor cells." (PMID 35883645, 2022). "TOP DNA panel identified KRAS (G12D), GNAS (R201C), and FBXW7 (R367*) variants in the primary tumor." (PMID 35255903, 2022). "The combined use of GDC-0994 and the MEK inhibitor cobimetinib demonstrated improved anticancer efficacy in KRAS- and BRAF-mutated tumor models." (PMID 36233210, 2022). "In this paper, we provide evidence that ATO/D-VC combination therapy is effective against KRAS mutant tumour growth." (PMID 36619305, 2022). "Compound 1 showed a moderate degree of internalization in MCF-7 cells and an effective combination of KRAS G-quadruplex DNA, thus exhibiting obvious tumor suppressor activity." (PMID 35630522, 2022). "The growing evidence that KRAS is a key modulator of the inflammatory tumor microenvironment and immune escape was recently extensively reviewed by Hamarsheh and colleagues." (PMID 35327394, 2022). "Blocking of CCL9 and IL-23 abrogates the lung tumor aggressiveness in KRAS/MYC-altered mice mainly by re-establishing a tumor-suppressive lung microenvironment." (PMID 36074553, 2022). "Other studies have identified that YAP1 overexpression regulated by PI3K is a way for tumor cells to evade KRAS inhibition." (PMID 36291766, 2022). "In mouse models, KRAS siRNA showed an improved accumulation for over 3 days and enhanced inhibition of tumor growth with the aid of BCPVs." (PMID 35652096, 2022). "First, we determined that the KRAS mutant allele frequency (MAF) positivity threshold was 0.72%, using non-tumour DNA extracted from formol-fixed paraffin-embedded (FFPE) healthy tissue samples with proven KRASWT status by NGS." (PMID 35194118, 2022). "In i3 tumor cells, published gene signatures related to MAPK activity and KRAS and BRAF activating mutations were more highly expressed." (PMID 35773407, 2022). "TUSC2 sensitizes KRAS/LKB1 tumors to carboplatin plus pembrolizumab through modulation of the immune contexture towards a pro-immune tumor microenvironment." (PMID 35210547, 2022). "As for 22 immune infiltrating cells, immune and stromal scores showed 11 and 6 kinds of tumors correlated with KRAS expression levels based on the tumor purity." (PMID 36330448, 2022). "All studies confirm that KRAS G12C inhibitors can only delay tumor progression before the tumor evolves mechanisms to escape." (PMID 35267628, 2022).
tumor (continued). "We collated a total of 159 tumor samples bearing BRAF mutations, 133 with NRAS mutations, 303 with KRAS mutations, and 96 with EGFR mutations from the URMC NGS database from June 2020 to July 2021." (PMID 35627184, 2022). "Administration of COMP7 to mice bearing established LUAD-PDX/KRAS xenograft tumors significantly decreased tumor volume and weight." (PMID 36377663, 2022). "In CRC with mutated KRAS, the upregulation of ASNS enables the tumor to adapt to high glutamine demands." (PMID 36035152, 2022). "In KRAS (G12C) positive cell lines and patient-derived xenograft models from multiple tumor types, 65% of the models showed significant tumor regression." (PMID 35922812, 2022). "In this study, mutated APC and KRAS, which are supposed to occur in the early sequence of ACS, supports what Fearon stated about the importance of mutational sequence in determining tumor biologic behavior." (PMID 35709138, 2022). "The injections of ATO, VC or D-VC alone had only weak and partial tumor suppressing effects, but the ATO and D-VC combination had much more potent KRAS-mutant tumor suppressing impact compared to the group of tumor-bearing mice injected with ATO and VC." (PMID 36359850, 2022). "Such insights are consistent with data elaborated in a switchable KrasG12D model, where FRA1 transfers tumor-forming capabilities in the KRAS “off” setting, demonstrating that the transcription factor can substitute signaling by the oncogene." (PMID 36534167, 2022). "KRAS is the predominant isoform mutated in cancer and the isoform mutated exclusively in PDAC, driving the tumor initiation, progression, and metastasis." (PMID 35652096, 2022). "Some miRNAs, such as let-7, miR-18a*, miR-30b, miR-143 and miR-145, have been shown to be tumor suppressors (since they inhibit KRAS expression) and potential biomarkers for predicting favorable responses to anti-EGFR therapy." (PMID 36230757, 2022). "KRAS is one of the most frequently mutated genes in cancers and its mutations are observed in more than 90% of PDAC patients involved in tumor formation and development." (PMID 35686109, 2022). "The entry of complex delivery systems into KRAS tumor cells is only the first step to achieve effective drug delivery, followed by the process of intracellular transport, dissociation and release of the drug payload." (PMID 35154489, 2022). "Concurrently, our GSEA results implied that PTX3 engaged in tumor immune and metabolism pathways such as the “inflammatory response”, “complement”, “KRAS signaling”, “arginine and proline metabolism”, and “Toll-like receptor signaling pathway”." (PMID 36139597, 2022). "The panel analysis, however, revealed the presence of KRAS G12D in the tumor because of a sufficient amount of nucleic acid (DNA: 16.48 ng; RNA: 196.96 ng) from washing fluid specimen." (PMID 35545933, 2022). "Accordingly, the marked and significant reduction of the tumour sizes by treatment with the αEGFR-mAB-P/KRAS-siRNA/P nanostructures can be explained by a combination of reduced proliferation and increased apoptosis in the respective tumours." (PMID 35220407, 2022). "In summary, this article outlines the fundamental roles of KRAS that govern the effects of tumor inflammation and provides insights into the development of novel prognostic biomarkers for early diagnosis and potential cancer therapeutics." (PMID 35563733, 2022). "The A459 tumour weights of the group treated with αEGFR-mAB-P/KRAS-siRNA/P nanostructures were significantly diminished in comparison to the control-siRNA loaded αEGFR-mAB-P/P nanostructure group." (PMID 35220407, 2022).
tumor (continued). "Mechanistically, PADC cells elevate the production of CCL2 chemokine to attract CCR2+ M2-like macrophage infiltration, which reciprocally provides tumor cells with abundant TGFβ to promote KRAS-independent tumor growth." (PMID 36230914, 2022). "KRAS is the first discovered human tumor gene, and KRAS protein is equipped with a nearly spherical structure with no obvious binding site, which makes it difficult to synthesize a compound that can target binding and inhibit its activity." (PMID 36118526, 2022). "We conclude that the αEGFR-mAB-P/KRAS-siRNA/P nanostructures reach the tumour, internalise into accessible cells and release the siRNA into the cytoplasm of tumour cells to induce the KRAS knockdown." (PMID 35220407, 2022). "In preclinical studies, KRAS c.34G > T (p.G12C) direct inhibitors were noted to upregulate a pro-inflammatory tumor microenvironment and enhance anti-tumor T cell activity." (PMID 36077640, 2022). "The constitutively active KRAS oncoprotein contributes to both tumor onset and cancer development by promoting cell proliferation and anchorage-independent growth in a MAPK pathway-dependent manner." (PMID 34489556, 2022). "Another immunomodulatory effect of KRAS-mutant tumors was found to be the downregulation of MHC class I molecules on the cell surface of tumor cells through MAPK-driven internalization and intracellular sequestration." (PMID 35965494, 2022). "The ORR was 50% for CAPIRI-Cet in patients with KRAS-WT tumours and the median PFS and OS were of 6.2 and 21.1 months, respectively." (PMID 36819803, 2022). "We showed that KRAS-mutant tumor cells exclusively respond to KRAS blockade in vivo, because the oncogene co-opts host myeloid cells via a C-C-motif chemokine ligand 2 (CCL2)/interleukin-1 beta (IL-1β)-mediated signaling loop for sustained tumorigenicity." (PMID 35327394, 2022). "Pancreatic cells surviving KRAS oncogene ablation show dormancy, are responsible for tumor relapse, and mostly rely on oxidative phosphorylation (OXPHOS) for survival." (PMID 35158815, 2022). "The waterfall chart of mutation analysis shows that in tumor samples positive for TRPC3 expression, they are also often highly mutated in KRAS gene loci (89.7%), and that the specific mutation type is missense mutation." (PMID 35330477, 2022). "KRAS mutations in NSCLC were associated with tobacco smoking, a high tumor mutational burden (TMB), and an inflammatory tumor microenvironment, along with high T-cell infiltration." (PMID 36741723, 2022). "It was indicated that miR-206 acts as a tumor suppressor miRNA in oral squamous cell carcinoma by directly targeting KRAS." (PMID 34489556, 2022). "The diagnostic accuracy of cfDNA analysis for the detection of KRAS mutations in NSCLC, compared with tumor tissue was shown in the Forest Plot for 39 studies, including 2,666 NSCLC patients." (PMID 36386815, 2022). "Comparing with cells harbouring sole KRAS or PI3K mutation, EGFR mutation can act on multiple signalling pathways in concert to well protect tumour cells from apoptosis." (PMID 35692096, 2022).
tumor (continued). "KRAS signaling is also thought to activate CXCL2 and its associated receptor CXCR2 resulting in suppressed immune response and tumor proliferation." (PMID 36033462, 2022). "Epithelial plasticity or EMT is a key cellular program that can be activated by KRAS contributing to tumor progression." (PMID 35562390, 2022). "ORR increased from 57% (n = 209) with chemotherapy alone to 64% (n = 232) with addition of cetuximab (p = 0·049) in patients with KRAS-WT tumours." (PMID 36819803, 2022). "The use of matched therapy was relatively low in patients with tumor alterations such as ERBB2 mutation (14/43, 32.6%), MET amplification (32/99, 32.3%), KRAS G12C (8/135, 5.9%), and EGFR exon 20 insertion (1/25, 4.0%)." (PMID 35877242, 2022). "PERSEIDA was an observational, prospective study assessing the cfDNA RAS (KRAS/NRAS) mutational status evolution in first-line, metastatic CRC, RAS wild-type (according to baseline tumor tissue biopsy) patients." (PMID 36551560, 2022). "Accumulating evidence revealed the potential anti-tumor activity of small molecules targeting KRAS G-quadruplex DNA molecules." (PMID 35630522, 2022). "ATO/D-VC has been shown an effective in suppressing tumour growth of the KRAS G12D mutant PDAC tumours." (PMID 36619305, 2022). "Nonetheless, AMG510 was not effective on the KRAS G12D mutation types because of the changed binding pocket and the tumor will quickly acquire resistance to KRAS G12C inhibition." (PMID 35785187, 2022). "Numerous mutated genes correlated with tumor therapy response, such as EGFR, KRAS, ARID1A, and SMARCA4." (PMID 36290859, 2022). "The aerobic glycolytic pathway is enhanced by the activation of oncoproteins such as KRAS and by the inhibition of tumor suppressor functions." (PMID 36293106, 2022). "Some clinical factors, including age, TNM stage, tumour markers (CEA and CA19-9), and genetic mutations (KRAS, NRAS, and BRAF), have been reported as risk factors for colorectal metastasis in previous studies." (PMID 35296011, 2022). "The two KRAS inhibitors demonstrated different anti-tumor efficacy and displayed synergistic or additive effects, when combined with downstream pathway inhibitors." (PMID 36139627, 2022). "The same four cancer driver pathways were identified by an SVM comparing these cell lines to disease-matched primary tumors, and in particular, the KRAS pathway had the lowest overall cell-line-tumor correlation." (PMID 36513728, 2022). "Autophagy is elevated in most KRAS-driven tumors, recycling metabolism precursors to support tumor growth, serving a pro-tumor role." (PMID 34459894, 2022). "For example, MAPK and cyclin-dependent kinase 4/6 inhibitors act in concert to suppress the proliferation of KRAS-mutant lung cancer cells by triggering the accumulation of NK cells within the tumor and promoting NK cell-dependent tumor cell killing." (PMID 34374809, 2022).